EEA1 (early endosome antigen 1)
Diseases named in the same sentence as EEA1 in open-access papers (continued):
Sharing a sentence is not in itself a finding about the gene and the disease.
infection (continued). "Within 15 min post-infection, a double-labeled immunofluorescence assay with anti-DENV envelope protein and anti-EEA1 antibodies showed colocalization, suggesting that the virus particles were translocated to the early endosomes after clathrin-mediated endocytosis." (PMID 20122152, 2010). "However, EEA1 and RSV show limited correlation even at 90 min post-infection which implies that RSV may favour fusion at the cell surface over fusion following internalization." (PMID 38015055, 2023). "The successful VSV-MeGFP-ZEBOV infection observed in the absence of drug in cells expressing NPC1-Halo alone or in combination with mScarlet-EEA1 indicates that NPC1-Halo is capable of facilitating infection and that VSV-MeGFP-ZEBOV trafficked to NPC1-Halo−containing endosomes." (PMID 32764148, 2020). "This did not change for Rab5 (data not shown) or EEA1 18 hours following infection." (PMID 24828674, 2014). "EEA1 staining was apparent after 5 min and persists up to 1 h post infection (data not shown)." (PMID 20011125, 2009). "An L2/EEA1 PLA signal was observed in both control and retromer knock-down cells eight hours after infection, confirming that retromer is not required for virus endocytosis." (PMID 25693203, 2015). "Expression of EEA-1, CREB-1 and TNFRI proteins was selectively observed after macrophage infection with 2D6 bacteria but not in the vacuoles of macrophages infected with the wild-type bacterium." (PMID 20359357, 2010). "Colocalization analysis of TLR9 to endosomal marker EEA1 in infected ArLa non-CIC showed that TLR9 partially colocalizes with endosomes at two hours and fully four hours after infection." (PMID 21079774, 2010). "It is also possible that ARF6 and EEA1, while proximal in infection, do not share a contiguous lumen (coupled); if such an event were the case, however, it would be difficult to imagine how a CIE cargo such as MHC-I ultimately partitions with EEA1." (PMID 30042195, 2018).
cancer (11 papers, 2011 to 2025). A tumor composed of atypical neoplastic, often pleomorphic cells that invade other tissues. "To further verify that CTSG enters cancer cells through endocytosis, we stained early endosome marker, early endosome antigen 1 (EEA1), together with CTSG." (PMID 41040318, 2025). "To analyze the association of Ago2 with endosomes, we observed that the levels of Ago2 overlapping with endosome marker EEA1 in A549 cancer cells were higher than that in BEAS-2B normal lung epithelial cells (Figs. 2Diii and EV2E)." (PMID 38649663, 2024). "Inhibition of TPC function in metastatic cancer cells has been shown to prevent trafficking of β1-integrin, leading to accumulation within EEA1-positive early endosomes and preventing cancer cell migration." (PMID 34466782, 2021). "Further, the analysis by confocal microscopy revealed EC-Fc on DTX-ECL was specifically internalized into HER2 overexpressing cancer cells and colocalized with EEA1, suggesting that DTX-ECL internalized into the cells via HER2 mediated pathway of endocytosis." (PMID 28946623, 2017). "The expression of RAB5A and EEA1 were significantly increased in aggressive cancer tissue compared to indolent diseased tissue (P ≤ 0.05)." (PMID 26473288, 2015). "However, we previously detected ASAH1 in early endosomes in cancer cell lines, as isolated by Endo-IP using EEA1 (early endosomal antigen 1) as the affinity handle 24, suggesting its localization in less mature endolysosomal compartments." (PMID 41279717, 2025). "In HeLa cells, more extensive co-localisation of AnxA2 and EEA1 was observed, possibly due to the increased Tyr23 phosphorylation of AnxA2, which is a typical feature of cancer cells such as HeLa and Tyr23 phosphorylation of AnxA2 is essential for its proper endosomal association." (PMID 23555942, 2013). "H. pylori strains that were negative for the cancer associated virulence factor CagA were detected in phagosomes that recruited large amounts of EEA1 relative to Rab5, compared to CagA positive strains." (PMID 21426584, 2011). "Interestingly in two independent datasets – the Chinese Cancer Genomics Consortium (CCGC) and REpository for Molecular BRAin Neoplasia DaTa (REMBRANDT) – EEA1 expression increases from normal brain to GBM, and survival is significantly better for patients with tumors having lower expression of EEA1." (PMID 29740146, 2018). "Although the staining patterns in the cancer tissues varied among cases by IHC, double IHF demonstrated that γ1-adaptin was mainly localized in EEA1-positive endosomes, but not in the TGN." (PMID 38265632, 2024). "The changes in APPL1 (3p21), RAB5A (3p24) and EEA1 (12q22) and RAB4A (1q42) in PIN or primary cancer tissue compared to their expression in non-malignant tissue may discriminate metastatic tissue and provide an avenue for monitoring disease progression." (PMID 26473288, 2015).
tumor (10 papers, 2017 to 2025). "After EGF exposure, the fraction of EGFR colocalizing with EEA1 increased for both tumor cell lines." (PMID 34572731, 2021). "Mouse recombinant YM1 decreased the enhanced level of ROS and the colocalized proportion of both xCT and EEA1 in irradiated tumor cells." (PMID 33959512, 2021). "Four genes increased concordantly in EGFR-amplified tumours in both primary and recurrent samples: EEA1 (co-localising early endosomal antigen 1 with the EGFR–EGF complex as it enters intracellularly), IVD (isovaleryl-coA dehydrogenase), SEC61G (co-expressed with EGFR on chr 7p11), and EGFR itself." (PMID 36765632, 2023). "Overall, however, these results suggested that YM1 produced by macrophages may contribute to promoting xCT expression and attenuate the EEA1-mediated capture of intracellular xCT in tumor cells during irradiation." (PMID 33959512, 2021). "Thus, further research is needed to determine whether YM1 and YKL39 attenuate EEA1-mediated xCT capture via the same mechanism in various tumor cases under γ-radiation." (PMID 33959512, 2021). "In BxPC-3 tumor cells, we detected EGFR trafficking to EEA1-positive early endosomes in all conditions tested, but colocalization was much more evident in cells treated with EGF or EGF and erlotinib (see arrows), in which EGFR was undergoing endocytosis." (PMID 34572731, 2021). "In 2D cultures, we found a low EGFR fraction colocalizing with EEA1-positive early endosomes in PANC-1 and BxPC-3 tumor cells." (PMID 34572731, 2021). "Additionally, we further demonstrated the increased colocalization of internalised PD-L1 with EEA1 (Early Endosome Antigen 1) and RAB 7, which are markers for early and late endosomes, respectively, in aT-sEV-treated tumour cells." (PMID 38719909, 2024). "The early endosomal autoantigen EEA1 was found in a yeast two-hybrid system to interact directly with RAB5B in a GTP-dependent matter, independent of intrinsic GTPase activity; in tumor cells, exosomes tended to localize with EEA1." (PMID 28589855, 2017).
bacterial infection (1 paper, 2025). "Rab4b and EEA1 have been shown to assist bacterial infection." (PMID 41244687, 2025).
epithelial carcinoma (1 paper, 2024). "A similar colocalization of HAdV2 with the EEA1 protein was observed in HeLa cells (human epithelial carcinoma cell line)." (PMID 38392896, 2024).
EEA1 also shares sentences with these, for which no sentence is quoted: pneumonia (2 papers); allergic bronchopulmonary aspergillosis (1); Alzheimer disease (1); amyotrophic lateral sclerosis 2 (1); bladder cancer (1); cystinosis (1); dementia (1); faciogenital dysplasia (1); metastatic disease (1); metastatic prostate carcinoma (1); Pick disease (1); rheumatoid arthritis (1); tuberculosis (1).